PMP22 (peripheral myelin protein 22)
Diseases named in the same sentence as PMP22 in open-access papers (continued):
Sharing a sentence is not in itself a finding about the gene and the disease.
axonal neuropathy (6 papers, 2020 to 2025). Any nerve disorder affecting the axon of a nerve. "In accordance with the protein’s high expression in Schwann cells, most PMP22 variants are known to cause demyelination, but at least one case of axonal neuropathy caused by a single nucleotide variant in PMP22 has been reported." (PMID 37606798, 2023). "In comparison, the PMP22 mutation p.Thr118Met causes HNPP in the heterozygous state and severe axonal neuropathy in the homozygous state." (PMID 37606798, 2023). "Therefore, our results further support the need to consider rare PMP22 mutations also when NCS suggests an axonal neuropathy." (PMID 37606798, 2023). "The most common form, CMT type 1A, results from a mutation in the Peripheral Myelin Protein 22 (PMP22) gene, leading to demyelination, whereas CMT type 2 encompasses axonal neuropathies caused by diverse genetic mutations." (PMID 40760337, 2025). "For instance, in patients with positive family history and demyelinating neuropathy, 70% have a duplication of the PMP22 gene (CMT1A), whereas in patients with positive family history and axonal neuropathy, 33% have a mutation in MFN2." (PMID 33324924, 2020).
diabetes (5 papers, 2011 to 2026). "Also, the ourquantitative study of myelinated nerve fibers clearlyshowed that myelin sheaths were unaffected by diabetes.Myelin infolding is associated with alterationsin myelin proteins such as P0, PMP22 and myelinassociatedglycoprotein (MAG)." (PMID 23671825, 2011). "Additional studies reporting androgen effects on peripheral nerves which originated in Melcangi’s laboratory described androgen protection of peripheral myelin containing the peripheral glycoprotein P0 and the peripheral myelin protein 22 (PMP22) from damage inflicted by injury, aging and diabetes." (PMID 38672445, 2024).
gastric cancer (5 papers, 2019 to 2025). A primary or metastatic malignant neoplasm involving the stomach. "Collectively, our results demonstrate a novel anti-apoptotic role of PMP22 in the progression of gastric cancer, suggesting that PMP22 might be an important diagnostic or therapeutic target for gastric cancers and other human diseases." (PMID 34421356, 2021). "Taken together, our data support an important regulatory role of miR-139-5p in gastric cancer, and suggest miR-139-5p and PMP22 might be important diagnostic or therapeutic targets for gastric cancers and other human diseases." (PMID 32174796, 2020). "Taken together, our data suggest an important regulatory role of miR-139-5p in gastric cancer, suggesting that miR-139-5p and PMP22 might be important diagnostic or therapeutic targets for gastric cancer and other human diseases." (PMID 32174796, 2020). "Taken together, our data suggest an important regulatory role of miR-139-5p in gastric cancer, and indicate that miR-139-5p and PMP22 might be important diagnostic or therapeutic targets for gastric cancers and other human diseases." (PMID 32174796, 2020). "MiR-139-5p targets NF-κB signal pathway negatively regulates PMP22 and gastric cancer cell proliferation." (PMID 36217151, 2022). "Overall, our results demonstrated that PMP22 overexpression enhanced the tumorigenicity of gastric cancer cells and also inhibited etoposide-induced tumor suppression." (PMID 34421356, 2021). "Taken together, these results demonstrated that the inhibition of PMP22 significantly suppressed gastric cancer cell proliferation." (PMID 34421356, 2021). "Compared with the expression level in a human glomerular microvascular endothelial cell line (HGMEC), PMP22 was upregulated in most of the gastric cancer cell lines." (PMID 34421356, 2021). "Taken together, our research provided an anti-apoptotic properties alternative mechanism for PMP22 in gastric carcinoma and suggested PMP22 can be a potential target for the treatment of gastric cancer." (PMID 34421356, 2021). "SGC7901 and HGC-27 gastric cancer cells were infected with lentivirus expressing either pLKO-shCtrl or pLKO-shPMP22 for 72 hours, and then the mRNA expression levels of PMP22 were then determined by RT-PCR assay." (PMID 34421356, 2021). "Overall, the involvement and functional mechanisms of PMP22 in gastric carcinoma are poorly understood." (PMID 34421356, 2021). "Our previous studies showed a requirement for PMP22 in self-renewal and chemoresistance in gastric cancer 22, however, there are few studies on the regulation of PMP22 in gastric cancer." (PMID 32174796, 2020). "The ectopic expression of PMP22 mRNA in tumor specimens of patients with gastric cancer is correlated with recurrence after perioperative chemotherapy, suggesting a crucial role of PMP22 in the resistance of chemotherapy." (PMID 31652725, 2019). "Here, we show that PMP22 regulates gastric cancer cell proliferation by inhibiting cell apoptosis." (PMID 34421356, 2021). "Few studies have examined the function and regulation of PMP22 in gastric cancer." (PMID 32174796, 2020). "In this study, we discovered a new miRNA that regulates PMP22 and gastric cancer cell prolifration." (PMID 32174796, 2020). "Here, we describe a new miRNA that regulates PMP22 and gastric cancer cell proliferation." (PMID 32174796, 2020). "The miR-139-5p might suppress the expression of PMP22 and tumor proliferation by inhibition of NF-κB signaling in gastric cancer, suggesting miR-139-5p and PMP22 might be important diagnostic or therapeutic targets for gastric cancer and other human diseases." (PMID 32174796, 2020). "Mechanistically, miR-139-5p may negatively regulate PMP22 to repress cell proliferation by targeting the NF-κB signaling pathway in gastric cancer." (PMID 32174796, 2020). "In gastric cancer cells, there is a conserved miRNA recognition site of miR-139-5p on the 3 'UTR of PMP22." (PMID 36217151, 2022).
gastric cancer (continued). "Therefore, PMP22 inhibition may be a good target for treatment of gastric cancer." (PMID 34421356, 2021). "Recently, more and more studies have shown that PMP22 play a great role in the physiological processes such as cells adhesion, migration, proliferation and tumorigenesis, but the involvement and functional mechanisms of PMP22 in Gastric carcinoma are not investigated clearly." (PMID 34421356, 2021).
Charcot-Marie-Tooth disease type 1 (4 papers, 2007 to 2023). Charcot-Marie-Tooth disease type 1 (CMT1) is a group of autosomal dominant demyelinating peripheral neuropathies characterized by distal weakness and atrophy, sensory loss, foot deformities, and slow nerve conduction velocity. "Charcot–Marie-Tooth type 1 are inherited demyelinating diseases affecting peripheral nerves which are caused in most patients by mutations in Pmp22 (CMT1A), MPZ (CMT1B), and GJB1 genes (CMT1X; see for review Suter and Scherer, 2003)." (PMID 24194699, 2013).
glioma (4 papers, 2016 to 2024). A benign or malignant brain and spinal cord tumor that arises from glial cells (astrocytes, oligodendrocytes, ependymal cells). "The volcano plot revealed that glial cells in C5 derived from TDL upregulated expression of myelin-related genes (TYMP, CD9, MAG, and PMP22) and immune-related and inflammatory response-associated genes (IL1B and CXCL8) comparing to those from glioma." (PMID 36085357, 2022). "However, there are few studies on the relationship between PMP22 and glioma, which need to be further explored." (PMID 39403379, 2024).
hearing loss (4 papers, 2018 to 2024). "The observation that a mouse model of CMT1E, which is caused by different alterations in the same gene as CMT1A (PMP22), has overt hearing loss (like some CMT1E patients) together with a distinct set of structural deficits in the cochlea, corroborates the specificity of the CMT1A phenotype." (PMID 39178128, 2024). "It seems difficult to conclude that variations in PMP22 could protect from hearing loss." (PMID 31393079, 2019).
pancreatic cancer (4 papers, 2020 to 2025).
scoliosis (4 papers, 2021 to 2025). A congenital or acquired spinal deformity characterized by lateral curvature of the spine. "The abnormal PMP22 variant might be linked with a phenotype of distal muscle weakness and atrophy, scoliosis, deformities of both thumbs and both feet, and elevated CSF protein and serum creatine kinase." (PMID 33726003, 2021). "Although most were associated with classic demyelinating phenotypes (55/75, 73.3%), there was considerable phenotypic heterogeneity such as prominent deep sensory disturbances (SH3TC2, PRX) and scoliosis (SH3TC2, MPZ, and PMP22)." (PMID 37519884, 2023).
auditory neuropathy (3 papers, 2019 to 2022). A hearing disorder characterized by impaired transmission of signals through the auditory nerve, resulting in mild to severe hearing loss and poor speech perception. "There are several types, and more than 80 genes have been identified; particularly 2 of them, MPZ and PMP22, have been associated with auditory neuropathy." (PMID 36529647, 2022).
carpal tunnel syndrome (3 papers, 2022 to 2023). Entrapment of the median nerve in the wrist that is characterized by numbness, tingling and painful movement. "We also probed a large human genetic database for which deidentified patient records are available, leading to the discovery that the T118M-encoding PMP22 missense mutation is a risk factor for chronic or repeated incidents of carpal tunnel syndrome (CTS)." (PMID 36581210, 2023).
colon carcinoma (3 papers, 2011 to 2022). "This correlation is supported by recent studies in clone A colonic carcinoma cells showing that PMP22 forms a complex with α6β4 integrin." (PMID 21518455, 2011). "However, PMP22 protein levels are significantly lower in colon cancer samples than in normal colonic tissues, possibly due to the low post-translational efficiency of PMP22 mRNA in these tissues and cells." (PMID 36217151, 2022). "PMP22 mRNA levels in colon cancer are not altered compared with normal tissue, yet protein levels, as measured by IHC and Western blot analysis, are significantly reduced in colon carcinoma samples compared with normal tissue." (PMID 31032403, 2019). "Furthermore, there is no substantial difference in the PMP22 mRNA level in colon cancer compared to normal tissues." (PMID 36217151, 2022).
colorectal cancer (3 papers, 2020 to 2023). A primary or metastatic malignant neoplasm that affects the colon or rectum.
Dejerine-Sottas disease (3 papers, 2023 to 2026). "Such rare PMP22 variants have been linked to CMT1 (denoted CMT1E when caused by PMP22 variants other than duplication), HNPP, or Dejerine-Sottas syndrome (DSS)." (PMID 37606798, 2023).
demyelinating disease (3 papers, 2021 to 2025). A broad group of disorders that affect the myelin sheaths that cover the neurons. "The transcriptional dynamics in Schwann cell differentiation resolved by scRNA-seq include genes associated with congenital demyelinating diseases such as Pmp22 (Charcot Marie Tooth and Deafness Syndrome) and Plp1 (Pelizaeus-Merzbacher disease)." (PMID 34003106, 2021).
schizophrenia (3 papers, 2010 to 2019). A major psychotic disorder characterized by abnormalities in the perception or expression of reality. "PMP22 seems to play an important role in regulating cell growth and myelination, functions that are disturbed in schizophrenia." (PMID 31118906, 2019).
schwannoma (3 papers, 2013 to 2024). A benign, usually encapsulated slow growing tumor composed of Schwann cells. "The combination is also able to down-regulate the expression of Pmp22 in cultured Schwannoma cells more efficiently than single drugs." (PMID 25491744, 2014). "Combination of (RS)-baclofen, naltrexone hydrochloride and D-sorbitol, termed PXT3003, improved myelination in the Pmp22 transgenic co-culture cellular model, and moderately down-regulated Pmp22 mRNA expression in Schwannoma cells." (PMID 25491744, 2014). "We then tested the potency of the three drugs to down-regulate Pmp22 expression in rat RT4 schwannoma when normalised to the levels of both Actb and Rps9 housekeeping genes." (PMID 25491744, 2014). "In pilot experiments using cultured Schwannoma cells, we were able to detect a limited but significant down-regulation of Pmp22 gene expression." (PMID 25491744, 2014). "However, BFABP, DHH, P0, PMP22 and PLP are not overexpressed in schwannomas or neural crest cells, but only in Schwann cell precursors." (PMID 23354516, 2013).
Smith-Magenis syndrome (3 papers, 2007 to 2025). Smith-Magenis syndrome (SMS) is a complex genetic disorder characterized by variable intellectual deficit, sleep disturbance, craniofacial and skeletal anomalies, psychiatric disorders, and speech and motor delay. "Also interesting is the possibility of overlap with Smith Magenis syndrome, in cases where the PMP22 deletion also includes the RAI1 gene." (PMID 41300731, 2025).
Tremor (3 papers, 2022 to 2024). An unintentional, oscillating to-and-fro muscle movement about a joint axis. "The significance of the abstract lies in the phenomenology and the physiology of the tremor seen in patients with genetically confirmed duplication of PMP22 gene." (PMID 38344215, 2024).
Charcot-Marie-Tooth disease type 1E (2 papers, 2022). A rare subtype of CMT1 characterized by a variable clinical presentation. "Trembler-J (Tr-J) mice carrying a spontaneous L16P mutation in the peripheral myelin protein 22 (PMP-22) are a well-established, clinically relevant model for Charcot-Marie-Tooth Disease Type 1E (CMT1E)." (PMID 36499770, 2022).
demyelinating (2 papers, 2025 to 2026). "Charcot-Marie-Tooth type 1A (CMT1A), a prevalent progressive demyelinating peripheral neuropathy is caused by a duplication of the peripheral myelin protein (PMP22) gene." (PMID 41825735, 2026).
endometriosis (2 papers, 2011 to 2025). The growth of functional endometrial tissue in anatomic sites outside the uterine body. "As dysregulation of α6 integrin has been implicated in disease biology of the endometrium, PMP22 may be an underappreciated potential target for diseases such as infertility, endometriosis, and endometrial cancer." (PMID 21518455, 2011). "In both SLE and endometriosis, PMP22 was highly enriched in FRUCTOSE_AND_MANNOSE_METABOLISM (NES = -1.5770, NP = 0.0162; NES = 1.9934, NP = 0.000)." (PMID 39744159, 2025). "Subsequently, by the intersection analysis, we obtained four overlapping genes (PMP22, QSOX1, REV3L, SP110) as potential co-diagnostic genes for SLE and endometriosis." (PMID 39744159, 2025). "Subsequently, by LASSO regression analysis, we constructed prediction models for 15 diagnostic genes in the endometriosis cohort and 6 diagnostic genes in the SLE cohort, respectively, and identified four co-diagnostic genes (PMP22, QSOX1, REV3L, SP110)." (PMID 39744159, 2025). "Collectively, PMP22, QSOX1, REV3L, SP110 may serve as potential diagnostic biomarkers for early diagnosis and targeted therapy of endometriosis and SLE." (PMID 39744159, 2025). "Four co-diagnostic genes (PMP22, QSOX1, REV3L, SP110) were identified for endometriosis and SLE." (PMID 39744159, 2025). "In this study, we found that PMP22 expression was significantly increased in endometriosis patients and decreased in SLE patients, which may be related to the complex post-transcriptional regulation of PMP22." (PMID 39744159, 2025). "The expression of PMP22, QSOX1 and SP110 were significantly higher in the ovarian endometriotic tissues from endometriosis patients compared to normal endometrial." (PMID 39744159, 2025).
facioscapulohumeral muscular dystrophy (2 papers, 2013 to 2022). An autosomal dominant disorder affecting the skeletal muscles of the face, scapula, and upper arm. "Molecular testing revealed both, a hereditary motor and sensory neuropathy type 1A (HMSN1A, also called Charcot-Marie-Tooth neuropathy 1A, CMT1A) due to a PMP22 gene duplication and facioscapulohumeral muscular dystrophy (FSHD) due to a partial deletion of the D4Z4 locus (19 kb)." (PMID 24041033, 2013).
hereditary motor and sensory neuropathy (2 papers, 2021 to 2025). A group of slowly progressive inherited disorders affecting motor and sensory peripheral nerves. "Hereditary motor and sensory neuropathy, also referred to as Charcot–Marie–Tooth disease (CMT), is most often caused by a duplication of the peripheral myelin protein 22 (PMP22) gene." (PMID 34171997, 2021).
liver cancer (2 papers, 2021 to 2025). An epithelial or non-epithelial malignant neoplasm that arises from the liver. "As a consequence of ARID1A deficiency-induced conformational alteration, the dysregulation of some genes such as PMP22 and GSC, promoted the invasion capacity of liver cancer cells." (PMID 34689165, 2021).
lung carcinoma (2 papers, 2019 to 2022). "The inhibition of PMP22 expression by miR-29 in lung cancer cells damages cell proliferation and metastasis, indicating that PMP22 is related to cancer progression." (PMID 36217151, 2022). "PMP22 gene expression was shown to be reduced in an animal model of lung cancer, whereas other investigations on lung cancer cells revealed PMP22 transcript amplification." (PMID 36217151, 2022). "The suppression of PMP22 expression in lung cancer cells by miR-29 impairs cell proliferation and invasion, and this result may suggest the involvement of PMP22 in progression of lung cancer." (PMID 31652725, 2019).
multiple sclerosis (2 papers, 2012 to 2013). A progressive autoimmune disorder affecting the central nervous system resulting in demyelination. "Frasson and coauthors described two cases of genetically confirmed CMT1A with duplication of PMP22 gene that also developed clinically definite multiple sclerosis." (PMID 24455342, 2013). "The 2 that were up-regulated, were only altered in the OB: Ptprz1 (protein tyrosine phosphatase, receptor-type, Z polypeptide 1) is expressed in the remyelinating oligodendrocytes of multiple sclerosis lesions; and Pmp22 (peripheral myelin protein 22) is a component of myelin." (PMID 22403656, 2012).
Myotonia (2 papers, 2021 to 2022). An involuntary and painless delay in the relaxation of skeletal muscle following contraction or electrical stimulation. "We describe a Chinese family affected by both CMT1A and myotonia with concomitant alterations in both the PMP22 and SCN4A genes." (PMID 34996390, 2022).
neuroblastoma (2 papers, 2019 to 2025). Neuroblastoma (NB) is the most common solid, extracranial childhood tumor. "MATN2 and glial differentiation marker PMP22 are among the upregulated genes induced by GLI family zinc finger 1 (GLI1) in SH-SY5Y neuroblastoma cells." (PMID 41189817, 2025). "Downregulation of tumor suppressor genes PMP22 and MATN2 is associated with high-risk neuroblastoma tumors." (PMID 41189817, 2025). "Expression of GFAP was reduced (nonsense versus shRNA CgA, 1.0±0.1 versus 0.02±0.01, P<0.05), whereas expression of PMP22 (1.0±0.02 versus 3.3±0.5, P<0.05) and SERPINF1 (1.0±0.1 versus 3.1±0.5, P<0.01) was increased in the shRNA CgA transfectants compared to nonsense control neuroblastoma cells." (PMID 30833285, 2019).